TMPRSS2 (transmembrane serine protease 2)
Diseases named in the same sentence as TMPRSS2 in open-access papers (continued):
Sharing a sentence is not in itself a finding about the gene and the disease.
COVID-19 (continued). "Heatmap showed upregulation of genes (e.g., TMPRSS2, JUN and CXCL8) related to the COVID-19 signalling pathway upon DCM treatment at a concentration of 200 μM, compared with concentrations of 0 μM and 100 μM." (PMID 37301869, 2023). "The repurposing of known TMPRSS2 and CTSL/CTSB inhibitors can become an effective and safe treatment option for COVID-19." (PMID 37990007, 2023). "Remarkably, ACE2 and TMPRSS2 are extremely important for SARS-CoV-2 to enter cells, but we hardly detected expressions of ACE2 and TMPRSS2 in the blood of COVID-19 patients." (PMID 37087411, 2023). "Several investigations have concluded that COVID-19 enters cells via the well-known receptor Angiotensin-Converting Enzyme 2 (ACE2) and the serine protease TMPRSS2." (PMID 37292255, 2023). "Our main aim is to try a molecular characterization in these main related genes (TMPRSS2, AR, ACE2 and MX1) to better understand COVID-19 severity; and trying to initiate the lines for molecular biomarkers in COVID-19 management." (PMID 37287057, 2023). "Both ACE2 and TMPRSS2 are needed for SARS-CoV-2 entry and the onset of infection and gastrointestinal symptoms of COVID-19 are due to targeting of TMPRSS2." (PMID 37559103, 2023). "We identified changes in lungs and kidneys of COVID-19 related genes ACE2 and TMPRSS2 in pneumonia and mechanical ventilation (PMV) and ischemic AKI-induced lung dysfunction." (PMID 35123426, 2022). "The transmembrane protease serine 2 (TMPRSS2) is considered to be one of the major host factors responsible for the virulence of SARS-CoV-2 and the pathogenesis of COVID-19." (PMID 36146616, 2022). "Cardiac injury can be triggered by a number of direct and indirect mechanisms including viral injury and the interplay with host cells (COVID-19 spike protein (S), ACE2 receptor, host serine protease TMPRSS2, cathepsin B, and cathepsin L)." (PMID 37386548, 2022). "To characterize the expression of SARS-CoV-2 receptors in the placenta due to COVID-19, we analyzed the pattern of ACE2, TMPRSS2 and CD147 in placental tissues derived from eight SARS-CoV-2+ pregnant patients, and comparing them with seven healthy placentae." (PMID 36177036, 2022). "This analysis indicates the relevant role of several markers such as TMPRSS2, CD45-, CD163/CD206, and CD33 for COVID-19 aggressiveness." (PMID 36969980, 2022). "Further studies are needed to assess the expression of TMPRSS2 across different age groups; indeed a reduced TMPRSS2 expression in younger compared to older individuals, as observed in mice and in preliminary human studies, could help explain age-related differences in COVID-19 morbidity." (PMID 35104687, 2022). "Here, we report the interesting role of TMPRSS2, CD45-, CD163/CD206, and CD33 in COVID-19 aggressiveness." (PMID 36969980, 2022). "In this study, we used a computational approach to investigate the expression patterns, molecular and functional characterization of CXCL10 and TMPRSS2 and their coexpressed genes in PRAD and COVID-19." (PMID 36239108, 2022). "This identification assisted in exploring the co-expressed genes of TMPRSS2 and CXCL10 responsible for prostate cancer and COVID-19 development by utilizing the TCGA data." (PMID 36239108, 2022). "Using our in silico approach, we identified changes in COVID-19 related genes ACE2 and TMPRSS2 in traditional mouse models of AKI and kidney-lung cross-talk." (PMID 35123426, 2022). "Angiotensin-converting enzyme 2 (ACE2) and TMPRSS2 facilitate SARS-CoV-2 infection in cells, and the TMPRSS2 inhibitor has been proposed as a potential treatment for COVID-19." (PMID 35475801, 2022). "Through abundant researches focused on COVID-19, we understand that SARS-CoV-2 enter infected cell mainly mediated by ACE2 and TMPRSS2." (PMID 35924838, 2022). "The transmembrane serine protease 2 (TMPRSS2) primes the SARS-CoV-2 Spike (S) protein for host cell entry and represents a promising target for COVID-19 therapy." (PMID 35804152, 2022).
COVID-19 (continued). "Expression of COVID-19 related genes ACE2 and TMPRSS2 was downregulated in lungs after 6 h of distant AKI effects." (PMID 35123426, 2022). "They observed that ACE2 was mainly located in the cell membrane, TMPRSS2 was mainly located in the nucleus and cytoplasm, and ACE2 and TMPRSS2 were extremely low in the heart of COVID-19 patients." (PMID 35387441, 2022). "Additionally, TMPRSS2 expression in COVID-19-infected lung tissues was significantly reduced compared to healthy lung tissues, indicating that a low TMPRSS2 expression may result in COVID-19 severity and death." (PMID 36364238, 2022). "To interpret the functional activity of TMPRSS2 and CXCL10 in prostate cancer and COVID-19, we used the set of previously determined co-expressed genes while using the PANTHER database." (PMID 36239108, 2022). "Since TMPRSS2-mediated SARS-CoV-2 entry into host cells, AAT was demonstrated to be capable to inhibit SARS-CoV-2 entry, and therefore can represent an anti-COVID-19 treatment." (PMID 35163482, 2022). "From the PPI network analysis results, it is evident that TMPRSS2 is a crucial factor in COVID-19 prognosis, as its nodes connect to ACE2 and as per previous studies, TMPRSS2 is a notable ACE2 primer." (PMID 36239108, 2022). "TMPRSS2 was positively correlated with the ratio of late EMT in COVID-19 and BSG was negatively correlated with the ratio of late EMT in COVID-19." (PMID 36248845, 2022). "Diabetes and periodontitis increase the expression of ACE-2 where ACE-2, TMPRSS2, and FURIN (highly expressed in the epithelial cells of the oral mucosa) play a crucial role in COVID-19 invasion." (PMID 35224542, 2022). "Based on these facts, it can be suggested that coexpressed genes of TMPRSS2 and CXCL10 in both PRAD and COVID-19 play an active role in mediating the pathways responsible for disease prognosis." (PMID 36239108, 2022). "Considering the pathophysiology of COVID-19, SARS-CoV-2 enters the host cells via the receptors of angiotensin-converting enzyme (ACE) type 2 with the additional help of transmembrane serine protease 2 (TMPRSS2) as the essential protease." (PMID 35369001, 2022). "TMPRSS2 and ACE2 expression were upregulated in COVID-19 patients but BSG, CTSL, FURIN expression was higher in IPF patients, suggesting their role in increased myofibroblast expression in COVID-19." (PMID 36248845, 2022). "A retrospective study examining COVID-19 heart autopsies, revealed that total ACE2, glycosylated ACE2, and TMPRSS2 protein expressions were higher in cardiomyocytes from autopsied and explanted hearts of diabetic than non-diabetic samples." (PMID 36009573, 2022). "At the onset of the COVID-19 pandemic, there were studies suggesting that higher ACE2 and TMPRSS2 levels may be associated with higher susceptibility to SARS-CoV-2 infection, and this spurred extensive research that unveiled novel insights into the function and biology of ACE2/TMPRSS2." (PMID 36560732, 2022). "We discovered that TMPRSS2 and CXCL10 are overexpressed in prostate cancer and COVID-19 using the UALCAN and GEPIA2 datasets." (PMID 36239108, 2022). "Afterward Venn diagrams were contrived using the Bioinformatics and Evolutionary Genomics web tool in order to show the lists representing common co-expressed genes of TMPRSS2 and CXCL10 in each of the cases of prostate cancer and COVID-19." (PMID 36239108, 2022). "In terms of host factors responsible for SARS-CoV-2 entry, the COVID-19 knowledge model highlights the importance of ACE2, TMPRSS2, and components of the ISG response that are specifically dysregulated by SARS-CoV host interaction (ACE2, SERPING1)." (PMID 39086962, 2022). "The COVID-19 spike protein binds to the ACEII receptor on human cells, and the human protease TMPRSS2 activates the spike protein and allows the viral entry, being paramount for viral spread and pathogenesis in the infected host." (PMID 35287158, 2022).
COVID-19 (continued). "We analyzed the underlying mechanism of thyroidal manifestations in patients with COVID-19 using ACE2 and TMPRSS2 immunostaining." (PMID 35625425, 2022). "Our current computational analysis examined the important natural TMPRSS2 variations and their interactions with the S glycoprotein and two potential serine protease inhibitors, which could be useful to develop high-affinity and personalized drugs for the treating of COVID-19 patients." (PMID 35207518, 2022). "In the present study, we have investigated the anti-COVID-19 activity of Mortaparib and MortaparibPlus against three target proteins, namely ACE2, TMPRSS2, and Mpro using bioinformatics approaches and cell-based assays." (PMID 34647577, 2021). "In this work, we used prospectively collected placental biopsies to assess the effect of COVID-19 severity on the expression of SARS-CoV-2 entry factors ACE2, TMPRSS2, and furin." (PMID 34257394, 2021). "In agreement, steroidal sex hormones (estradiol, progesterone and testosterone) are implicated in the age-dependent and sex-specific severity of COVID-19 through mechanisms including modulation of the immune responses and ACE2 and/or TMPRSS2 levels." (PMID 33920748, 2021). "Their role in COVID-19 is widely documented because ACE2 allows the binding of SARS-CoV-2 in the lung cells and TMPRSS2 acts as protein priming for the virus." (PMID 34360824, 2021). "TMPRSS2 and Neuropilin-1, the key components that facilitate SARS-CoV-2 infection, are potential targets for treatment of COVID-19." (PMID 34168096, 2021). "We found that SARS-CoV-2 entry factors, including ACE2, TMPRSS2, FURIN, and NRP1, have elevated expression in nasal squamous cells from male individuals with moderate and severe COVID-19." (PMID 34330889, 2021). "Also, the developmental regulation of TMPRSS2 may make infants and children immune from COVID-19." (PMID 34016183, 2021). "Therefore, TMPRSS2 inhibitors may also be part of COVID-19 therapy." (PMID 34445368, 2021). "The spike glycoprotein of SARS-CoV-2, the virus responsible for COVID-19, allows for entry into cells via human angiotensin converting enzyme II (ACE2) once primed by the cellular serine protease TMPRSS2." (PMID 33853637, 2021). "We aim to investigate the plausible link of tissue SARS-CoV-2 viral entry gene expression, such as TMPRSS2 and ACE2, with infection and death by gender during the COVID-19 pandemic in the United States." (PMID 34832534, 2021). "Although research is still in its early stages, the differences in sex hormones appear to modulate the expression of ACE-2 and transmembrane serine protease 2 (TMPRSS2), both of which are involved in determining viral entry and viral development of COVID-19." (PMID 33665612, 2021). "In a second approach, four COVID-19-related proteins, the host cell proteins ACE2 and TMPRSS2 as well as the viral proteins 7a and S protein were computationally analyzed as potential heme-binding proteins with an experimental validation." (PMID 33925394, 2021). "SARS-CoV-2 entry via the olfactory epithelium and the increase in the expression of TMPRSS2 with ACE2 facilitates SARS-CoV-2 neurotropism and then dysautonomia in long COVID-19 patients." (PMID 34884216, 2021). "In this sense, ACE2 and TMPRSS2 are crucial for SARS-CoV-2 infection and potential pharmacological targets for COVID-19 treatment." (PMID 33920748, 2021). "Further research proving the clinical significance of ACE2 and TMPRSS2 levels in SARS-CoV-2 infection and COVID-19 severity is required." (PMID 33706759, 2021). "Additionally, considering the inhibitory effects on ACE2 and TMPRSS2 gene expression, we hypothesize the inclusion of the present EOs in protection devices, such as chirurgical masks, functioning as physical barriers against COVID-19." (PMID 33809983, 2021).
COVID-19 (continued). "One recent study has described that BPA exposure may affect the expression of key severe acute respiratory syndrome coronavirus 2 (SARS-CoV-2) infection mediators such as angiotensin-converting enzyme 2 (ACE2), transmembrane serine protease 2 (TMPRSS2), and furin in human tissues." (PMID 33804363, 2021). "Recently, we have conducted in silico analyses that revealed potential hypothalamic microRNAs that can be used to identify potential therapeutic targets to treat neurological symptoms in COVID-19 patients via the regulation of ACE2 and TMPRSS2." (PMID 33802995, 2021). "As TMPRSS2 expression in the human lungs seems to be modulated by estrogens and androgens, data suggest that the activation of estrogen pathways or inhibition of androgen pathways may be a new target for therapeutic clinical intervention for symptom amelioration in COVID-19 patients." (PMID 34222852, 2021). "However, data from ACE2 and TMPRSS2 expression on different airway tract sites of SARS-CoV-2 infected individuals is still sparse and have been raising divergent hypothesis about their potential impact on COVID-19 susceptibility." (PMID 33958627, 2021). "The molecular mechanism is quite clear between cancers and COVID-19 where ACE2, cytokines, TMPRSS2, and coagulation are prominent." (PMID 33912588, 2021). "During the COVID-19 pandemic, it has been further demonstrated that SARS-CoV-2 can use CTSB and CTSL as well as TMPRSS2 for priming host cells." (PMID 34820418, 2021). "The efforts are directed to mask the COVID-19 functional receptors on human cells, ACE2 and TMPRSS2." (PMID 33777332, 2021). "Patients with GI cancers can be more vulnerable to COVID-19 than the general population due to higher expression of ACE-2 and TMPRSS2, which can serve as entry route for SARS-CoV-2 into target cells." (PMID 34399734, 2021). "Recent studies on the pathophysiology of COVID-19 are indicating that the Angiotensin convertase enzyme 2 (ACE-2) and transmembrane serine protease 2 (TMPRSS2) can act as a major component in the fusion of SARS-Cov-2 with target cells." (PMID 34399734, 2021). "This Comment explores the interaction between COVID-19 and cancer with attention paid to the modulation by cancer treatments of both ADAM17 and TMPRSS2, the proteases which control ACE2 processing, the SARS-CoV-2 target." (PMID 33531686, 2021). "TMPRSS2 and ACE-2 co-expression in GI could be the entry route for SARS-CoV-2 virus in absorptive enterocytes of the colon and ileum, resulting in further damage to the mucous membrane barrier, the development of inflammatory cytokine production, and the GI symptoms associated with COVID-19." (PMID 34768321, 2021). "Giving ACE2 and TMPRSS2 as specific targets of COVID-19, the plasma membrane and the lipid raft in which ACE2 and TMPRSS2 are embedded can actively participate in viral infection." (PMID 34638539, 2021). "ACE2 expression level is hardly detective in peripheral blood or lung compared with NRP1 and TMPRSS2, and ACE2 downregulation after viral infection increases the severity of COVID-19 disease." (PMID 34168096, 2021). "In this panel we included SARS-CoV-2 cyto-DEGs, the genes coding cytokines that are elevated in humans with severe COVID-19 obtained by manual data collection from published studies and SARS-CoV-2 receptors ACE2 and TMPRSS2—in total 55 genes 3,17–24." (PMID 34045585, 2021). "Here, we used a multitude of different methods to analyze the distribution of SARS-CoV-2 virus, ACE2, and TMPRSS2 in 25 different organs, using formalin-fixed paraffin-embedded (FFPE) autopsy specimens from deceased COVID-19 patients." (PMID 34440669, 2021). "We are currently optimizing MM3122 and this class of inhibitors for TMPRSS2 selectivity and antiviral potency and, in due course, will test MM3122 and other optimized leads in appropriate animal models of COVID-19." (PMID 34635581, 2021).
COVID-19 (continued). "COVID-19 is due to infection with severe acute respiratory syndrome coronavirus 2 (SARS-CoV-2), which uses the receptor ACE2 and the protease TMPRSS2 for entry into host cells, thereby infecting cells of the respiratory tract and the oral cavity." (PMID 34299289, 2021). "Here, we leveraged the post-acute COVID-19 sequelae data and compared the relationships between the COVID-19 sequelae in multiple organ systems and the status of ACE2 and TMPRSS2 expression." (PMID 34094637, 2021). "Finally, the more similar the expression and distribution of ACE2 receptors and TMPRSS2 is in an animal species to expression and distribution of the same protein and protease in humans, the more likely that animal will display symptoms of COVID-19 similar to those seen in humans." (PMID 34359172, 2021). "Few studies have reported the direct effects of COVID-19 on the HPA axis, however, a recent study showed HPA to be rich in ACE2 receptors and TMPRSS2." (PMID 34336866, 2021). "Whereas anti-COVID-19 activity was studied in lung adenocarcinoma H1299 cells, where the gene expression of ACE2 and TMPRSS2 was measured after extract treatment." (PMID 34361576, 2021). "The human serine protease serine 2 TMPRSS2 is involved in the priming of proteins of the severe acute respiratory syndrome coronavirus 2 (SARS-CoV-2) and represents a possible target for COVID-19 therapy." (PMID 33375616, 2020). "ACE2, and TMPRSS2 protease promote SARS-CoV-2 infectivity, while inflammatory cytokines IL-6, or G-CSF worsen COVID-19 severity." (PMID 33245731, 2020). "In contrast to enhanced levels of TMPRSS2, T2 inflammation, whether observed in vivo or induced with IL-13 stimulation, precipitated a marked reduction in levels of epithelial ACE2, thus making it difficult to predict how T2 inflammation might affect overall risk for a poor COVID-19 outcome." (PMID 33046696, 2020). "This suggests that apart from ACE2 expression, regulation of miR-421, TMPRSS2, and ADAM17 is important to understand COVID-19 pathogenesis." (PMID 32948238, 2020). "Entry of SARS-CoV-2, etiological agent of COVID-19, in the host cell is driven by the interaction of its spike protein with human ACE2 receptor and a serine protease, TMPRSS2." (PMID 33029570, 2020). "In conclusion, we obtained the worldwide case fatality rates of COVID-19 and genetic information on the IFITM3, ACE2, TMPRSS2, and IL6 genes." (PMID 33396837, 2020). "Therefore, TMPRSS2 could represent a valid alternative target in COVID-19." (PMID 33143053, 2020). "Both ACE2 (an entry receptor) and TMPRSS2 (used by the virus for spike protein priming) are key proteins to SARS-CoV-2 cell entry, enabling progression to COVID-19 in humans." (PMID 32574196, 2020). "The Renin-Angiotensin-Aldosterone System (RAAS) has been shown to be central in COVID-19, since three of the key modulators of SARS-CoV-2 infectivity–angiotensin 1–7, ACE2, and AT1—belong to the RAAS, in addition to the TMPRSS2 expression." (PMID 32850920, 2020). "Current understanding of COVID-19 suggests that the virus uses angiotensin converting enzyme-2 (ACE-2) receptor and the cellular protease transmembrane protease serine 2 (TMPRSS2) to enter target cells." (PMID 32825011, 2020). "Here, we report that platelets from COVID-19 patients are hyperactive, and demonstrate, for the first time, that platelets express ACE2 and TMPRSS2." (PMID 32887634, 2020). "Although our findings show a significant role of androgens in mediating expression of TMPRSS2 and ACE2, the full array of mechanisms responsible for the gender disparities observed in COVID-19 outcomes is likely multifactorial." (PMID 33310900, 2020). "Due to a more extensive evaluation of TMPRSS2 and SARS-CoV-2 proteases, ACE2 seems to be a relatively good, less evaluated, starting point for potential COVID-19 therapies." (PMID 33260592, 2020).